FABP5 (fatty acid binding protein 5)
Description:
Intracellular carrier for long-chain fatty acids and related active lipids, such as endocannabinoids, that regulate the metabolism and actions of the ligands they bind. In addition to the cytosolic transport, selectively delivers specific fatty acids from the cytosol to the nucleus, wherein they activate nuclear receptors. Delivers retinoic acid to the nuclear receptor peroxisome proliferator-activated receptor delta; which promotes proliferation and survival. May also serve as a synaptic carrier of endocannabinoid at central synapses and thus controls retrograde endocannabinoid signaling. Modulates inflammation by regulating PTGES induction via NF-kappa-B activation, and prostaglandin E2 (PGE2) biosynthesis during inflammation (By similarity). May be involved in keratinocyte differentiation.
Synonyms: E-FABP; PA-FABP; KFABP; EFABP; PAFABP
Tractability: Small molecule: a structure with a bound ligand is known; a high-quality ligand is known; it has a binding pocket of medium quality. Antibody: its Gene Ontology location is reachable by antibodies, with high confidence; UniProt places it where antibodies can reach, with medium confidence. PROTAC: ubiquitination databases record sites on it; its protein half-life has been measured; a small molecule that binds it is known.
Target class: Fatty acid binding protein family; Auxiliary transport protein
Gene: Protein-coding gene on chromosome 8 (81,280,535 to 81,284,777, forward strand). Ensembl gene ENSG00000164687.
Subcellular location: Cytoplasm; Nucleus; Synapse; Postsynaptic density; Secreted
Subcellular location (Human Protein Atlas): Cytosol; Plasma membrane
Pathways (Reactome):
Developmental Biology: Differentiation of Keratinocytes in Interfollicular Epidermis in Mammalian Skin
Immune System: Neutrophil degranulation
Metabolism: Triglyceride catabolism
Signal Transduction: Signaling by Retinoic Acid
Gene Ontology:
Molecular function: fatty acid binding; identical protein binding; long-chain fatty acid transmembrane transporter activity; protein binding; lipid binding; lipid transporter activity; retinoic acid binding
Biological process: lipid transport across blood-brain barrier; long-chain fatty acid transport; epidermis development; fatty acid transport; lipid metabolic process; positive regulation of cold-induced thermogenesis; regulation of retrograde trans-synaptic signaling by endocanabinoid; triglyceride catabolic process; positive regulation of peroxisome proliferator activated receptor signaling pathway; regulation of prostaglandin biosynthetic process; regulation of sensory perception of pain; retrograde trans-synaptic signaling by endocannabinoid
Cellular component: cytoplasm; cytosol; extracellular exosome; nucleus; azurophil granule lumen; extracellular region; nucleoplasm; plasma membrane; postsynaptic density; secretory granule membrane; synapse; glutamatergic synapse; postsynaptic cytosol; postsynaptic density, intracellular component
Genetic constraint (gnomAD): Loss-of-function variants: 4 observed, 10.91 expected, observed/expected ratio (o/e) 0.37, 90% interval 0.18 to 0.84. The upper end of that interval is the gene's LOEUF score, 0.84, which puts it in group 3 of 6, group 1 being the genes least tolerant of losing a copy. Missense variants: 98 observed, 113.78 expected, observed/expected ratio (o/e) 0.86, 90% interval 0.73 to 1.02. Synonymous variants: 30 observed, 36.78 expected, observed/expected ratio (o/e) 0.82, 90% interval 0.61 to 1.11.
Homologues: Orthologues: chimpanzee FABP5 (100% identical), guinea pig FABP5 (89% identical), rat Fabp5 (81% identical), mouse Fabp5 (80% identical), pig FABP5 (78% identical), rabbit FABP5 (64% identical), dog FABP5 (62% identical), zebrafish fabp4a (47% identical), zebrafish fabp4b (40% identical), Caenorhabditis elegans lbp-7 (37% identical), Caenorhabditis elegans lbp-8 (33% identical), Drosophila melanogaster fabp (33% identical), and 2 more. Paralogues in human: PMP2 (54% identical), FABP4 (51% identical), FABP12 (50% identical), FABP3 (49% identical), FABP9 (49% identical), FABP7 (44% identical), CRABP1 (32% identical), RBP1 (30% identical), CRABP2 (29% identical), RBP5 (29% identical), RBP7 (29% identical), RBP2 (27% identical), and 3 more.
Diseases named in the same sentence as FABP5 in open-access papers:
FABP5 is named in the same sentence as 227 diseases in open-access papers, as found by Europe PMC text mining. Sharing a sentence is not in itself a finding about the gene and the disease. The quoted sentences say what the papers report.
breast carcinoma (71 papers, 2008 to 2025). "In summary, while FABP4 and FABP5 play distinct roles in regulating lipid availability for tumor cells, both are associated with poor prognoses in breast cancer." (PMID 40106183, 2025). "We found that distinct expression profiles of FABP4 and FABP5 were associated with their unique roles in breast cancer development." (PMID 40106183, 2025). "Previous studies also showed that the FABP5-PPARβ/δ pathway involved in cell proliferation is associated with AKT phosphorylation in breast cancer cells." (PMID 30167092, 2018). "It has been previously shown in a Her2 overexpressing mouse model that loss of FABP5 decreases murine mammary tumor growth, in part due to loss of host FABP5." (PMID 25779666, 2015). "A correlation with RA resistance in breast cancer tumors has been attributed to the high expression level of FABP5 which has been associated with poor prognosis in cancer." (PMID 25260874, 2014). "FABP5 is associated with psoriasis; it is a chronic immune-mediated disease that appears on the skin, breast cancer, and metastasis." (PMID 22811706, 2012). "Previous papers showed that FABP5 could promote the activation of NF-κB activity in prostate and breast cancer cell lines and FABP5 deficiency could impair macrophages mediated inflammation." (PMID 40016284, 2025). "It is of great interest to understand whether and how FABP4 and FABP5 link dysregulated lipid metabolism to breast cancer risk and progression." (PMID 40106183, 2025). "FABP5 is linked to breast cancer proliferation and resistance, whereas serum and tumor FABP4 levels were found to be significantly higher in BC patients than that of healthy controls and were positively connected with tumor size, aggressiveness and lymph node involvement." (PMID 31941087, 2020). "To determine whether the enhanced growth-inhibitory effects of curcumin and RA on mammary carcinoma cells were likely due to associated changes of FABP5 expression, we sought to assess the effect of curcumin on FABP5 expression in MDA-MB-231 cells." (PMID 25260874, 2014). "A question that arises from these observations is whether activation of the FABP5/PPARβ/δ path underlies tumor development in cancers other than specific breast cancers." (PMID 20847935, 2010). "Given the established link between obesity-associated lipid dysregulation increased breast cancer risk, FABP4 and FABP5 play critical roles in facilitating fatty acid oxidation and metabolism, as well as promoting oncogenic lipid signaling pathways." (PMID 40106183, 2025). "To investigate the role of FABP4 and FABP5 in breast cancer development, we first assessed their expression patterns in normal adjacent breast tissue specimens collected from patients with breast cancer." (PMID 40106183, 2025). "Emerging evidence from our group and others has shown that FABP4 and FABP5 play critical roles in breast cancer development and progression in preclinical models." (PMID 40106183, 2025). "In this study, we comprehensively analyzed the expression profiles of FABP4 and FABP5 in both normal and breast cancer tissues to assess their clinical significance and potential therapeutic implications." (PMID 40106183, 2025). "FABP5 promotes breast cancer progression by regulating lipid metabolism and interacting with lipid-associated macrophages (LAMs) in the tumor microenvironment." (PMID 40717587, 2025). "Altogether, the different expression patterns/levels of FABP4 and FABP5 in invasive breast cancer suggested their distinct roles in breast cancer development and progression." (PMID 40106183, 2025). "Clinical studies have illustrated that FABP5 overexpression is closely linked with poor clinical outcomes in HCC, colorectal cancer, and breast cancer, and it has emerged as a key oncogenic driver in liver tumorigenesis." (PMID 41357200, 2025).
breast carcinoma (continued). "During the early stages of human breast cancer, recruited inflammatory macrophages express FABP5, a regulator of lipid droplet accumulation and immunostimulatory cytokine secretion." (PMID 38411356, 2024). "FABP5 is a potentially targetable protein and therapeutic biomarker for the treatment of Dox resistance in breast cancer." (PMID 37538178, 2023). "In summary, the PPARγ and CaMKII axis mediated by FABP5 plays a crucial role in breast cancer chemoresistance." (PMID 37538178, 2023). "Clinical breast cancer patient's tumor tissues were evaluated by immunohistochemistry to determine FABP5 and p-CaMKII protein expression." (PMID 37538178, 2023). "Decreased tumor growth and lung metastasis were observed in FABP5-/- mice orthotopically injected with murine breast cancer cells, and clinical FABP5 RNA levels correlated with EGFR expression and poor prognosis." (PMID 35740306, 2022). "Noy’s team constructed two breast cancer MMTV-neu transgenic mouse models expressing different FABP5/CRABP-II ratios in breast tissue." (PMID 36611922, 2022). "In breast cancer cells, PPARβ/δ activity seems to be tightly regulated via fatty-acid-binding protein 5 (FABP5)." (PMID 35954274, 2022). "Similar to the effects observed in mammary carcinomas, activation of the FABP5/PPARβ/δ pathway was shown to promote cell survival, proliferation, and anchorage-independent growth in prostate cancer cells." (PMID 35954274, 2022). "Mechanism study reveals that FABP5 silencing reduces intracellular fatty acid (FA) levels then suppressed NF‐κB signalling that leads to reduction of the downstream target genes in breast cancer cells." (PMID 33837625, 2021). "FABP5 is also overexpressed in breast cancer cells in contact with adipocytes and correlates with tumour aggressiveness." (PMID 34359819, 2021). "The epidermal-type fatty acid-binding protein-5 (FABP-5) gene acts as a key molecule in the development and progression of a variety of tumors like breast cancer and hepatocellular carcinoma." (PMID 32328135, 2020). "NF-kappaB increases via direct transcriptional activation the expression of FABP5 in MCF-7 breast cancer cells, which stimulates proliferation." (PMID 32375405, 2020). "In breast cancer, FABP5-PPARβ/δ functions downstream of EGFR signaling to promote tumor cell proliferation." (PMID 33352874, 2020). "In aggressive prostate and breast cancer cells, FABP5 knockdown repressed the expression of genes involved in lipolysis, including HSL and MAGL, as well as that of genes involved in de novo FA synthesis, such as ELOVL6 and ACSL1." (PMID 33128030, 2020). "The correlation between overexpression of FABP5 and malignant potential of tumors and metastasis in several cancers such as prostate, esophageal and breast cancer has been previously reported." (PMID 31391093, 2019). "FABP5 has been shown to stimulate PPARβ/δ transactivation in a breast cancer cell line (MCF-7 cells)." (PMID 30877402, 2019). "In our study, both the rate-limiting lipase ATGL and FA transporter FABP5 acted as accelerators of breast cancer, and the latent relationship between these two molecules deserves further investigation." (PMID 29914512, 2018). "Further, immunohistochemistry was performed to detect differential expression of ATGL and FABP5 in breast cancer tissue sections." (PMID 29914512, 2018). "Abrogation of ATGL and FABP5 sharply attenuated the malignancy of co-cultivated breast cancer cells." (PMID 29914512, 2018). "FABP4 and CD36 were scarcely expressed in breast cancer cell lines in the current study, so we focused on FABP5." (PMID 29914512, 2018). "ATGL and FABP5 were then ablated to investigate their impact on the aggressiveness of breast cancer cells that were surrounded by adipocytes." (PMID 29914512, 2018). "It is noteworthy that in this study, we discovered the protumoral role of FABP5 through intracellular FA transportation and signaling activation in breast cancer cells with the presence of adipocytes." (PMID 29914512, 2018).
breast carcinoma (continued). "FABP5 expression was proved to be detectable in endothelial cells, lung epithelium, macrophages, adipocytes, and breast cancer cells." (PMID 29237483, 2017). "In MMTV-ErbB2/HER2 mice, spontaneously developing breast-cancer, FABP5 ablation relieves activation of EGFR downstream signals, down-regulates NR1C2 target-genes involved in cell-proliferation and suppresses tumor-growth." (PMID 26894976, 2016). "In ATRA-resistant MMTV-neu transgenic-model of breast-cancer, decreasing FABP5/CRABP-II ratio diverts ATRA from NR1C2 to RAR and suppresses tumor-growth." (PMID 26894976, 2016). "Our data indicate that CRABP1, in conjunction with previously identified CRABP2 and FABP5, plays a key role in breast cancer cell response to RA." (PMID 26142905, 2015). "Our studies show that FABP5 has a role in both host and tumor cell during breast cancer progression." (PMID 25779666, 2015). "Taken together, this suggests a role for FABP5 in the macrophage during breast cancer progression and metastasis." (PMID 25779666, 2015). "Since we observed a correlation between FABP5 and EGFR in breast cancer patient samples, we further analyzed the functional and mechanistic relationship between FABP5 and EGFR in TNBC cells." (PMID 25779666, 2015). "In, we established a stable shRNA FABP5 knockdown (FABP5 KD) MDA-MB-231 cell line to test the necessity of FABP5 in breast cancer." (PMID 25779666, 2015). "We analyzed FABP5 expression in a tissue microarray (TMA) constructed of 423 primary breast cancer patient samples." (PMID 25779666, 2015). "In our studies, we show FABP5 is an excellent biomarker for breast cancer in a TMA containing a large cohort of 423 patient samples." (PMID 25779666, 2015). "Next, we employed the metastatic murine breast cancer cell line E0771 to determine if host FABP5 plays a role in distant metastasis." (PMID 25779666, 2015). "In order to fully grasp the scope of FABP5 in breast cancer, we next studied its role in the cancer cell." (PMID 25779666, 2015). "FABP5 has been shown to be involved in a variety of cancers including colon, prostate, and breast cancer." (PMID 25779666, 2015). "Decreased tumor growth and lung metastasis were observed in FABP5−/− mice othotopically injected with murine breast cancer cells." (PMID 25779666, 2015). "FABP5 in the breast tumor environment is also important in breast cancer progression and metastasis." (PMID 25779666, 2015). "The fact that TNBC cell lines, MDA-MB-231 and MDA-MB-468, express high levels of FABP5 and are resistant to retinoid therapy suggests that by suppressing the expression level of FABP5, these subtypes of breast cancer cells can overcome RA resistance." (PMID 25260874, 2014). "One approach to overcome resistance of mammary carcinoma cells to retinoic acid is to target and suppress the FABP5/ PPARβ/δ pathway." (PMID 25260874, 2014). "The mRNA and protein expression of the nuclear receptor, PPARβ/δ which binds to ligands delivered by FABP5 was also examined in the various breast cancer cell lines." (PMID 25260874, 2014). "In mammary carcinoma cells expressing high levels of FABP5, FABP5 delivers RA to PPARβ/δ, enhances the transcriptional activity of PPARβ/δ and activates PPARβ/δ target gene, PDK1 and VEGF-A." (PMID 25260874, 2014). "The importance of FABP5 as a prognostic marker in breast cancer patients was studied in a cohort of breast tissues, pinpointing that elevated levels of FABP5 was correlated with tumor grade and poor prognosis." (PMID 25260874, 2014). "Retinoic acid facilitates the growth of mammary carcinoma cells which express high levels of fatty acid-binding protein 5 (FABP5)." (PMID 25260874, 2014). "Our studies demonstrate that curcumin can be used to overcome RA resistance in mammary carcinoma cells since curcumin suppresses FABP5 expression level, reducing the delivery of RA to PPARβ/δ and downregulating the expression of PPARβ/δ target gene." (PMID 25260874, 2014).